RAB44 (RAB44, member RAS oncogene family)
Description:
The small GTPases Rab are key regulators of intracellular membrane trafficking, from the formation of transport vesicles to their fusion with membranes. Rabs cycle between an inactive GDP-bound form and an active GTP-bound form that is able to recruit to membranes different sets of downstream effectors directly responsible for vesicle formation, movement, tethering and fusion (By similarity). Promotes mast cell degranulation upon IgE Fc receptor (FcERI)-mediated activation.
Synonyms: dJ431A14.3; RASD3; RASL13
Tractability: Antibody: UniProt places it where antibodies can reach, with high confidence; its Gene Ontology location is reachable by antibodies, with high confidence.
Gene: Protein-coding gene on chromosome 6 (36,697,826 to 36,733,184, forward strand). Ensembl gene ENSG00000255587.
Subcellular location: Cell membrane; Lysosome membrane
Subcellular location (Human Protein Atlas): Vesicles
Pathways (Reactome):
Immune System: Neutrophil degranulation
Metabolism of proteins: RAB geranylgeranylation
Gene Ontology:
Molecular function: G protein activity; protein binding; GTP binding; GTPase activity; calcium ion binding
Biological process: mast cell degranulation; establishment of localization in cell; leukocyte activation involved in immune response; vesicle-mediated transport
Cellular component: lysosomal membrane; azurophil granule membrane; plasma membrane; specific granule membrane; bounding membrane of organelle; early endosome membrane; endoplasmic reticulum membrane; specific granule
Genetic constraint (gnomAD): Loss-of-function variants: 59 observed, 71.23 expected, observed/expected ratio (o/e) 0.83, 90% interval 0.67 to 1.03. The upper end of that interval is the gene's LOEUF score, 1.03, which puts it in group 4 of 6, group 1 being the genes least tolerant of losing a copy. Missense variants: 1,047 observed, 1,100.3 expected, observed/expected ratio (o/e) 0.95, 90% interval 0.9 to 1. Synonymous variants: 423 observed, 453.84 expected, observed/expected ratio (o/e) 0.93, 90% interval 0.86 to 1.01.
Homologues: Orthologues: chimpanzee RAB44 (99% identical), macaque RAB44 (92% identical), pig RAB44 (69% identical), dog RAB44 (67% identical), rabbit RAB44 (64% identical), mouse Rab44 (60% identical), rat Rab44 (59% identical), guinea pig RAB44 (57% identical), tropical clawed frog rab44 (30% identical), zebrafish rab44 (16% identical). Paralogues in human: RASEF (17% identical), RAB26 (9% identical), RAB37 (9% identical), RAB3A (8% identical), RAB3C (8% identical), RAB3D (8% identical), RAB3B (8% identical), RAB15 (8% identical), RAB6A (8% identical), RAB12 (8% identical), RAB6B (7% identical), RAB27A (7% identical), and 56 more.
Diseases named in the same sentence as RAB44 in open-access papers:
RAB44 is named in the same sentence as 22 diseases in open-access papers, as found by Europe PMC text mining. Sharing a sentence is not in itself a finding about the gene and the disease. The quoted sentences say what the papers report.
basophilic leukaemia (2 papers, 2020 to 2021). "To examine differences among human Rab44 and its mouse two isoforms, we expressed various Rab44 mutants in the rat basophilic leukemia cell line, RBL‐2H3, which is the most useful model for studying mast cells." (PMID 33641252, 2021). "Here, we investigated secretion and localization of the human long Rab44 isoform and the two mouse isoforms and their mutants expressed in rat basophilic leukemia (RBL)‐2H3 cells." (PMID 33641252, 2021). "When long-form mouse Rab44 is expressed in the rat basophilic leukaemia cell line RBL-2H3, it is mainly localised in the lysosomes." (PMID 32612275, 2020).
allergies (1 paper, 2024). "Considering that Rab44-KO mice exhibit lower levels of CAIA-induced inflammation, it is likely that Rab44 deficiency reduces wide-range immune responses, such as allergies and autoimmune diseases." (PMID 39595070, 2024). "In addition to allergies, Rab44 is likely to be involved in autoimmune diseases." (PMID 39595070, 2024).
anaphylaxis (1 paper, 2021). An acute hypersensitivity reaction that occurs from exposure to an allergen. "We recently used Rab44‐deficient mice to demonstrate that Rab44 regulates granule exocytosis in mast cells and IgE‐mediated anaphylaxis." (PMID 33641252, 2021).
Arthritis (1 paper, 2024). Inflammation of a joint. "Real-time PCR analyses indicated that Rab44-KO CAIA mice exhibited decreased expression levels of arthritis-related marker genes." (PMID 39595070, 2024). "To test whether Rab44 is involved in the development of inflammation during arthritis, we induced CAIA in WT and Rab44-KO mice." (PMID 39595070, 2024).
atopic asthma (1 paper, 2024). An asthma that is characterized by symptoms that are triggered by an allergic reaction caused by inhaled allergens such as dust mite allergen, pet dander, pollen and mold. "A study using transcriptome data reported that immune patients with atopy and atopic asthma have differential expression levels of the Rab44 gene compared to normal individuals." (PMID 39595070, 2024).
autoimmune (1 paper, 2024). "A study using whole-genome sequencing reported that a missense mutation in the Rab44 gene was found in T cells from patients with the autoimmune CD4-lymphoproliferative disease." (PMID 39595070, 2024).
fibromyalgia (1 paper, 2014). A chronic disorder of unknown etiology characterized by pain, stiffness, and tenderness in the muscles of neck, shoulders, back, hips, arms, and legs. "Fibromyalgia has been genetically linked to the HLA region (6p21.3) 63, which includes several genes associated with Notch signalling (e.g. Notch4, FKBP5, TNXB, MTCH1 and TNF-a) or with stem cell maintenance and proliferation (e.g. POU5F1, Flot1, MAPK14, Rgl2 and Rab44)." (PMID 25164209, 2014).
leukemia (1 paper, 2022). A malignant (clonal) hematologic disorder, involving hematopoietic stem cells and characterized by the presence of primitive or atypical myeloid or lymphoid cells in the bone marrow and the blood. "Our previous study indicated that Rab44 protein associates with vesicle-associated membrane protein 8 (VAMP8), a v-SNARE protein, in native mouse bone marrow mast cells as well as ectopic expression cells of rat basophilic leukemia-2H3." (PMID 35743062, 2022).
melanoma (1 paper, 2022). A malignant, usually aggressive tumor composed of atypical, neoplastic melanocytes. "Furthermore, Rab44 expressed in B16-F1 melanoma cells was found to interact with both endogenous p150Glued and the endogenous dynein heavy chain." (PMID 36126775, 2022).
tuberculosis (1 paper, 2020). A chronic, recurrent infection caused by the bacterium Mycobacterium tuberculosis. "The DEPs such as RAB44 and TPN involved in viral myocarditis, transcriptional misregulation in cancer, and tuberculosis can be used as potential markers of spleen immune response after ALV-J infection in chickens." (PMID 32799626, 2020).
immune diseases (1 paper, 2024). "Genetic studies have suggested that human Rab44 is involved in immune diseases." (PMID 39595070, 2024).
RAB44 also shares sentences with these, for which no sentence is quoted: asthma (3 papers); breast carcinoma (2); African trypanosomiasis (1); autoimmune disease (1); autoimmune thyroid disease (1); cancer (1); infection (1); prion disease (1); staphylococcus aureus infection (1); tumor (1); viral myocarditis (1).